PRXL2A (peroxiredoxin like 2A)
Description:
Involved in redox regulation of the cell. Acts as an antioxidant. Inhibits TNFSF11-induced NFKB1 and JUN activation and osteoclast differentiation. May affect bone resorption and help to maintain bone mass. Acts as a negative regulator of macrophage-mediated inflammation by inhibiting macrophage production of inflammatory cytokines, probably through suppression of the MAPK signaling pathway.
Synonyms: C10orf58; FAM213A; PAMM; MGC4248; Adrx
Tractability: Antibody: UniProt places it where antibodies can reach, with high confidence; its Gene Ontology location is reachable by antibodies, with medium confidence. PROTAC: ubiquitination databases record sites on it; a small molecule that binds it is known.
Gene: Protein-coding gene on chromosome 10 (80,406,443 to 80,437,115, forward strand). Ensembl gene ENSG00000122378.
Subcellular location: Cytoplasm; Secreted
Gene Ontology:
Molecular function: antioxidant activity
Biological process: regulation of osteoclast differentiation; cellular oxidant detoxification
Cellular component: cytoplasm; extracellular region
Genetic constraint (gnomAD): Loss-of-function variants: 25 observed, 24.53 expected, observed/expected ratio (o/e) 1.02, 90% interval 0.74 to 1.42. The upper end of that interval is the gene's LOEUF score, 1.42, which puts it in group 5 of 6, group 1 being the genes least tolerant of losing a copy. Missense variants: 237 observed, 271.59 expected, observed/expected ratio (o/e) 0.87, 90% interval 0.78 to 0.97. Synonymous variants: 94 observed, 102.2 expected, observed/expected ratio (o/e) 0.92, 90% interval 0.78 to 1.09.
Homologues: Orthologues: chimpanzee PRXL2A (99% identical), macaque PRXL2A (99% identical), rabbit PRXL2A (90% identical), dog PRXL2A (89% identical), guinea pig PRXL2A (88% identical), mouse Prxl2a (87% identical), pig PRXL2A (87% identical), rat Prxl2a (86% identical).
Diseases named in the same sentence as PRXL2A in open-access papers:
PRXL2A is named in the same sentence as 9 diseases in open-access papers, as found by Europe PMC text mining. Sharing a sentence is not in itself a finding about the gene and the disease. The quoted sentences say what the papers report.
oral squamous cell carcinoma (6 papers, 2020 to 2023). "PRXL2A was overexpressed in oral squamous cell carcinoma and renal clear cell carcinoma, where high PRXL2A was associated with poor prognosis." (PMID 38283944, 2023). "High PRXL2A expression is positively correlated with poor prognosis of oral squamous cell carcinoma, and a decrease in PRXL2A expression can significantly inhibit cell proliferation, migration and invasion." (PMID 35743699, 2022). "miR-125b has been found to upregulate peroxiredoxin-like 2A (PRXL2A), an antioxidant protein commonly upregulated in oral squamous cell carcinoma (OSCC), which inhibits the cellular oxidative damage by positive regulation of the Nrf2 signaling pathway." (PMID 35006436, 2020). "It has been confirmed that overexpression of PRXL2A and lymph node metastasis is related to poor outcomes in oral squamous cell carcinoma (OSCC) patients, suggesting that downregulation of miR-125b inhibitory molecules is the basis for the upregulation of PRXL2a in OSCC." (PMID 34490047, 2021). "In oral squamous cell carcinoma (OSCC), it was observed that the overexpression of the Peroxiredoxin-like 2A (PRXL2A) gene was induced by miR-125b, which successively suppresses the oxidative stress damage driven by positive feedback loops involving the NRF2 signaling pathway." (PMID 33287295, 2020).
cancer (4 papers, 2020 to 2024). A tumor composed of atypical neoplastic, often pleomorphic cells that invade other tissues. "PRXL2A is an essential protein in cancer stem cells that modulates redox status and maintains stemness properties." (PMID 38283944, 2023).
tumor (4 papers, 2019 to 2023). "miR-125b-5p acts mainly as a tumour suppressor in many different ways, for example, interacting with VEGF (vascular endothelial factor), PARP 1 (poly-ADP-ribose-polymerase 1) and PRXL2A (peroxiredoxin like 2A gene, responsible for anti-oxidative processes)." (PMID 38139300, 2023). "Compared with normal tissues, tumor tissues had increased mRNA levels of GNG3 and PRXL2A and a reduced mRNA level of ITIH3." (PMID 35743699, 2022). "According to the UALCAN website EC study cohort, tumor tissues have lower expression of ITIH3 protein (p < 0.001) and higher expression of PRXL2A protein (p < 0.001) than normal tissues." (PMID 35743699, 2022).
hematological disease (1 paper, 2022). "In addition, genes associated with hematological disease (e.g., PDE7A, LMAN1, F13A1, OLR1) and mitochondrial biogenesis and redox (e.g., NOS3, ALDH5A1, PRXL2A, SLC25A13, CPT2) were also significantly altered in BPD patients." (PMID 35484630, 2022).
infection (1 paper, 2025). The state of being infected such as from the introduction of a foreign agent such as serum, vaccine, antigenic substance or organism. "HTi pDCs also showed elevated RUBCNL (autophagy),59BCL11A (enhances Bcl-2 and pDC development), and PRXL2A (redox regulation), reinforcing the notion of autophagy activation and mitochondrial stress in response to infection." (PMID 41321641, 2025).
PRXL2A also shares sentences with these, for which no sentence is quoted: sarcoidosis (2 papers); adenoma (1); mouth ulcers (1); renal clear cell carcinoma (1).